NUS1P3 (NUS1 pseudogene 3)
Synonyms: YDD19
Gene: Processed pseudogene on chromosome 13 (24,328,211 to 24,329,072, forward strand). Ensembl gene ENSG00000234627.
Diseases named in the same sentence as NUS1P3 in open-access papers:
NUS1P3 is named in the same sentence as 4 diseases in open-access papers, as found by Europe PMC text mining. Sharing a sentence is not in itself a finding about the gene and the disease. The quoted sentences say what the papers report.
breast tumours (1 paper, 2022). "The methylation level of non-protein coding genes MIR124-2, NUS1P3 and RP11-713P17.4 was enriched in BBM tumours compared to primary breast tumours." (PMID 35058523, 2022). "This suggests that RP11-713P17.4 and NUS1P3 are frequently methylated in BBM but not in BP, and MIR124-2 methylation frequency is enriched BBM compared to primary breast tumours." (PMID 35058523, 2022).
tumours (1 paper, 2022). "Of these, the promoter regions of three genes (MIR124-2, RP11-713P17.4, and NUS1P3) were hypermethylated in BBM and three genes (MIR3193, CTD-2023M8.1 and MTND6P4) were hypomethylated in BBM relative to the primary tumours." (PMID 35058523, 2022).
NUS1P3 also shares sentences with these, for which no sentence is quoted: breast carcinoma (1 paper); cancer (1).